CRP (C-reactive protein)
Diseases named in the same sentence as CRP in open-access papers (continued):
Sharing a sentence is not in itself a finding about the gene and the disease.
infection (continued). "Moreover, within the infected group, the copy numbers of mtDNA bound by red blood cells positively correlated with patient CRP concentrations (R2 = 0.715, p < 0.001), indicative of an association between mtDNA copy numbers bound to red blood cell surfaces and infection severity." (PMID 40046178, 2024). "Similarly, despite infection, CRP levels are also associated with CRS." (PMID 38956649, 2024). "Additionally, EXTEM MCF was found to have the highest diagnostic accuracy for these infections (Area Under the Curve, 0.841; sensitivity 90.0%; specificity 90.4%), surpassing that of C-reactive protein and the Erythrocyte Sedimentation Rate (p = 0.006 and p = 0.019, respectively)." (PMID 39203582, 2024). "In addition, concomitant usage of TBCB-based CRP strategy and mNGS may distinguish infection from non-infection and identify the causative pathogen to reduce the misuse of antibiotics." (PMID 37408612, 2023). "Additionally, immunosuppressive agents may increase the risk of infection and block the production of several inflammatory markers (serum CRP, IL‐6, etc.), which could impair accurate diagnosis of PJI." (PMID 36181336, 2022). "CRP, as a component of the innate immune system, during infection may recognize various pathogens associated molecular patterns (PAMPs) such as phospholipid fragments released from damaged cells consequently activating the complement system and finally inducing the death of the targeted cells." (PMID 35741168, 2022). "Therefore, it suggested that PCT and CRP might respond differently to infection at different sites, and enteric-borne infection might cause higher levels of PCT and CRP." (PMID 36177334, 2022). "It is therefore possible that CRP measurement, which belongs to the standard armamentarium of general practitioners, may be valuable in identifying patients at risk for a more severe course of the infection." (PMID 35222429, 2022). "Moreover, high CRP levels are associated with hospital re-admissions and infection severity." (PMID 36477474, 2022). "However, HAdV serotype infections with respiratory symptoms could cause a higher increase in CRP concentration." (PMID 36649001, 2022). "Therefore, monitoring CRP parameters could be useful to recognize patients who are susceptible to infection in the first two days after hospitalization." (PMID 36518854, 2022). "Current evidence suggests that the use of promising diagnostic markers like CD11b, CD64, IL-6, IL-8, PCT, and CRP, either alone or in combination, might be helpful when considering to discontinue antibiotics at 24–48 h of onset of the suspected infection process." (PMID 35345614, 2022). "Although the recent literature misses many reports, routine blood tests including those for C-reactive protein, inflammatory markers, immunoglobulin G, and other indications may aid in determining the cause of infection, inflammation, and the immunological state." (PMID 36614809, 2022). "Similarly, in research by Kawasaki and co-authors, significantly higher CRP and IL-6 concentrations were found in patients with respiratory system infections caused by HAdVs as compared with infections caused by influenza viruses or respiratory syncytial viruses (RSV)." (PMID 36649001, 2022). "Our primary objective was to define associations between CRP ≥2 mg/L and the risk of death from infection, cardiovascular disease, or other causes, including stratification by chronic diseases previously shown to be associated with increased risk of infection death." (PMID 35535512, 2022). "The observation that patients who developed CS-AKI required a longer duration of ventilator therapy and that elevated parameters of the inflammatory response (CRP and white blood cell count) could be associated with a higher risk of infection is consistent with the literature data." (PMID 34573933, 2021). "In addition, high CRP/alb ratio associated with postoperative infections (p = 0.026)." (PMID 33740951, 2021).
infection (continued). "Furthermore, it may predispose to a delay in detecting active infection because of the masking effect of a suppressed C reactive protein (CRP) response." (PMID 33435949, 2021). "Indeed, EC could help postpone a switch in antimicrobial therapy when the CRP level increases during hospitalization caused by inflammation that is other than infection." (PMID 34649512, 2021). "Biomarkers such as lactate, C-reactive protein (CRP) and procalcitonin have a well-established role in identifying septic patients who are at risk of further deterioration, but as of yet a specific biomarker to detect the presence of a secondary infection remains elusive." (PMID 34856937, 2021). "IL-6 is the key cytokine triggering increased liver production of acute-phase proteins (APPs) such as C-reactive protein (CRP) and fibrinogen, causing a hypercoagulable disease that is characterized by thrombotic and embolic events, and may predict severity of infection." (PMID 32635302, 2020). "Except for Vitamin D, Ca++ and CRP levels, maternal hemogram was done in two different laboratories for each cohort and helminth diagnostic only for the Gabonese cohort, whereby we attempted to reduce the probability of infection to a maximum by using a questionnaire in the German group." (PMID 31673046, 2019). "Furthermore, mean values of CDAI scores and CRP levels measured during 1-year follow-up in each patient were calculated, thereby avoiding the effect of transient aggravation due to causes other than CD, such as infection." (PMID 30286108, 2018). "It is clinically important to evaluate the role of CRP as a predictor of the worst infectious conditions, such as the occurrence of MIAC and HCA, because the information for maternal CRP associated with infection might induce changes in the management of PPROM in most clinical settings." (PMID 26942752, 2016). "Les objectifs secondaires dans ce travail seront d’établir une association entre d'une part la valeur de la CRP et d'autre part l'incidence de la défaillance d'organes, la durée du séjour en réanimation, la durée de jours sous hémofiltration, la prévalence de l'infection." (PMID 26301005, 2015). "Moreover, greater trust was placed in CRP, which was used to determine whether the patient’s infection was caused by bacteria or viruses." (PMID 26141740, 2015). "However preoperative CRP concentrations in complicated patients were already significantly higher compared to those who do not develop complications, questioning if there was underlying infection prior to surgery." (PMID 25132018, 2014). "We observed evidence of heterogeneity in treatment effects across studies which might be accounted for by a number of factors such as severity of baseline infection or CRP levels, different underlying patient co-morbidities or medications, or variation in treatment modalities." (PMID 24155956, 2013). "Hence such findings might indicate the clinical usefulness of CRP levels as a source of diagnostic as well as a prognostic parameter of unapparent infection in critically ill septic cancer patients." (PMID 23634180, 2013). "Other factors in addition to shock and organ dysfunction, however, may cause the prolonged elevation of CRP (for example, higher risk of secondary infection or difficult elimination of present infection in these severe conditions), and these still remain to be explored." (PMID 17598889, 2007). "Preoperative CRP elevation and the presence of an infection membrane influenced sensitivity: sonication generally detected more bacteria (59-81%) than tissue samples (49-73%), though discrepancies remained." (PMID 41594072, 2026). "Collected data included age, gestational age at birth, mode of delivery, vaccination status, clinical presentation, length of hospital stay, C-reactive protein (CRP) levels, seasonality of infection, and use of antibiotic therapy." (PMID 41901540, 2026).
infection (continued). "Secondary outcomes included postoperative day 4 inflammatory markers (WBC and CRP), length of stay, and infection-related endpoints." (PMID 41899202, 2026). "Among neonates with low vitamin D (≤10 ng/mL), a higher proportion were CRP positive (57/95, 60%), indicating active infection/inflammation." (PMID 41531449, 2026). "Only four studies measured C-reactive protein (CRP) levels to exclude cases with elevated serum ferritin due to infection." (PMID 41572874, 2026). "Postoperative infection markers (C-reactive protein and erythrocyte sedimentation rate) were temporarily elevated due to surgical trauma and returned to normal during follow-up." (PMID 41602932, 2026). "Patients with complicated infection were more likely to display fever and elevated CRP at presentation, while leukocyte and neutrophil numbers did not significantly differ." (PMID 42237343, 2026). "Logistic regression showed an unadjusted AUC of 0.53 (95%-CI 0.45-0.62) for calprotectin and a binary outcome of infection compared to an AUC of 0.63 (95%-CI 0.55-0.71) for CRP." (PMID 42209889, 2026). "Five readily available markers were identified as independent predictors: the presence of local infection, platelet count, and C-reactive protein, procalcitonin (PCT), and CD64 levels." (PMID 41892483, 2026). "As expected, the infection group had significantly higher CRP values (15.29 ± 4.11 mg/L), in comparison with the neoplasia group (4.86 ± 1.56 mg/L) and the other conditions group (4.43 ± 3.21 mg/L), with statistical significance (ANOVA p < 0.01)." (PMID 41594176, 2026). "Clinicians need to carefully interpret the changes in CRP and avoid excessive anti-infection treatment." (PMID 41867931, 2026). "The POP-Score was designed to explore associations with elevated C-reactive protein (CRP), as an early infection/inflammation marker, in term and late-preterm neonates." (PMID 42196812, 2026). "PCT levels begin to rise within 3–6 h of infection onset and peak at 12–24 h, making it an earlier marker than CRP." (PMID 41597433, 2026). "Pre- and postoperative infection parameters (leukocytes, CRP) were recorded, and preoperative clinical findings were used to classify suspected infection." (PMID 41594072, 2026). "At infection onset, median temperature, and C-reactive protein (CRP) levels were lower than at CRS/ICANS diagnosis (37.2°C vs 38.4°C; P < .001 and 3.9 vs 6.0 mg/L; P = .002)." (PMID 42281893, 2026). "For example, C-reactive protein (CRP) was higher (mean 74.5 mg/L) in those with a current infection compared to those who were convalescent (mean 35.1 mg/L)." (PMID 41917819, 2026). "CRP levels are elevated due to intestinal inflammation, infection, and inflammation other than intestinal lesions." (PMID 41014055, 2026). "In the present study, inflammatory markers, including ESR and CRP, showed a steady decline after surgery in both groups, reflecting effective infection control." (PMID 41496122, 2026). "The CRP in plasma begin to increase 4 to 6 hours after the onset of infection, and reached the peak at about 24 to 48 hours." (PMID 41496026, 2026). "To assess potential confounding from acute inflammation, we performed a sensitivity analysis excluding patients with CRP ≥ 50 mg/L or documented infection, leaving 172 patients for analysis." (PMID 41601642, 2026). "Although PTGBD initially improved the inflammatory response, C-reactive protein levels subsequently rebounded, indicating inadequate infection control." (PMID 42281719, 2026). "Accumulating evidence demonstrates that CRP plays a fundamental role in inflammatory processes and the host’s response to infection." (PMID 41584825, 2026). "Persistent postoperative bloody-serous discharge and elevated infection markers such as C-reactive protein suggested early periprosthetic joint infection, prompting two surgical revisions." (PMID 42117028, 2026).
infection (continued). "A statistically significant difference was found between patients with URTI and LRTI in terms of CRP, tachypnea, dyspnea, duration of fever, duration of hospital stay due to infection, need for intensive care unit, and oxygen requirements (p < 0.05)." (PMID 41716706, 2026). "The increase of ESR was much slower than that of CRP at the time of infection, and a CRP/ESR ratio ≥0.5 had high specificity to depict the presence of infection." (PMID 41972130, 2026). "C-reactive protein (CRP) is a recognized biochemical marker of system-wide inflammation and generally rises with increasing infection severity." (PMID 41753020, 2026). "During infection, acute-phase proteins such as CRP and SAA1 leak into the alveolar space due to increased pulmonary vascular permeability." (PMID 40572197, 2025). "Pay attention to infection indicators such as white blood cells, C-reactive protein and calcitoninogen, as well as changes in body temperature." (PMID 41169413, 2025). "In abdominal surgery, a meta-analysis evaluating CRP to predict postoperative infection stated that CRP performs best three to four days after surgery." (PMID 40549692, 2025). "C-reactive protein (CRP) is an inflammatory marker produced during infection ortissue damage in the body." (PMID 39801415, 2025). "Further studies should correlate CRP kinetics with other inflammatory markers (e.g., pro-inflammatory cytokines, haptoglobin) and relevant clinical outcomes, such as surgical site infection or implant failure." (PMID 41472138, 2025). "Regarding biomarkers of infection, both groups had similar levels of C-reactive protein (CRP), IL-6 and procalcitonin, which suggested that the severity of COVID-19 infection were similar between groups." (PMID 39911872, 2025). "CRP is a protein produced in the liver during the acute phase response to tissue injury, infection, or other inflammatory stimuli." (PMID 37415393, 2025). "To assess the relative contributions of C3-dependent and -independent mechanisms to the CRP-driven immunity, we tested bacterial clearance of C3−/− mice with an elevated infection dose of 5 × 107 CFU, which WT mice were able to survive." (PMID 41214213, 2025). "Although the criteria for infection were chosen to minimise confirmation bias, there is still potential bias of the CRP analysis since the choice to obtain microbiological cultures and administer antibiotics is likely influenced by CRP levels." (PMID 40319081, 2025). "The different infection-related pathways of calprotectin and CRP are a potential explanation for the findings of our study." (PMID 40319081, 2025). "C-reactive protein (CRP) is produced by the liver and is elevated in tissue injury and infections, and is a marker of inflammation." (PMID 40208300, 2025). "Water-referenced metabolite concentrations were compared between the patients and controls and correlated with infection severity, as measured by maximum C-reactive protein (CRPmax) assay during inpatient admission." (PMID 41169742, 2025). "CRP is an acute inflammatory marker, and its level will increase significantly in an inflammatory state, which can sense infection or injury site of the body in time." (PMID 41281287, 2025). "Markers of infection and inflammation such as CRP, ESR, and LDH were also higher in our severe cases than in mild cases, in line with previous findings." (PMID 40487016, 2025). "While inflammatory markers (CRP, leukocytes, neutrophils) were higher in complicated infections, they were paradoxically lower in ESBL cases." (PMID 41009834, 2025). "C-reactive protein is an acute-phase protein produced in the liver after tissue damage, infection, or other inflammatory stimuli." (PMID 39852142, 2025). "Effectiveness was assessed through monitoring of infection signs, serum CRP levels, and microbiological outcomes." (PMID 40566131, 2025).
infection (continued). "Across all eight dimensions, the laser-treated group demonstrated significantly attenuated infection accumulation, with pronounced divergence in healing time, pain score, CRP levels, scar thickness, and return-to-activity duration (all p < 0.001)." (PMID 41357482, 2025). "Leukocyte count, ESR, and CRP levels correlated with the degree of joint inflammation and infection, impacting incision healing." (PMID 39854482, 2025). "Of the 55 anemic pregnant women, 9(16.4%) of them had inflammation or infection with high serum CRP levels (>5 mg/l)." (PMID 39928589, 2025). "C-reactive protein, procalcitonin, white blood cells, erythrocyte sedimentation rate, and the duration of antibiotic treatment were used as indicators of infection treatment." (PMID 39931362, 2025). "This study evaluates the use of exosomes derived from a bovine leukocyte spleen extract (IMMUNEPOTENT CRP), loaded with gentamicin, to improve infection control and promote wound healing in a diabetic setting." (PMID 41394149, 2025). "We included suspected infections from patients who had both CRP measurements and were treated with antibiotics within 14 days following index blood culture collection." (PMID 40764898, 2025). "Our data suggest that the recognition of bacterial amyloids by structurally altered CRP is critical for protection against prolonged infection." (PMID 40740789, 2025). "CRP has a half-life of approximately 19 hours, and it begins to rise 6–12 hours after the onset of infection, reaching its peak 24–48 hours later." (PMID 41169360, 2025). "Like other biomarkers, NLR has recently been combined with CRP to heighten the specificity and sensitivity for the identification of infection in dialysis patients." (PMID 39621113, 2025). "The infection control rate in the CRP+PCT+ group (60.3% ± 6.9) was significantly lower than that in the CRP-PCT- group (87.1% ± 7.8%)." (PMID 40160471, 2025). "Infection parameters were mildly elevated (C-reactive protein (CRP), 8.1 (norm < 5 mg/L), leukocytes 10.3 × 109/L (norm 4–9 × 109/L)." (PMID 41245990, 2025). "CRP promotes the recruitment of immune cells to sites of injury or infection, contributing to the local inflammatory response." (PMID 40529435, 2025). "Plasma C-reactive protein (CRP) is widely used as a biomarker for bacterial infections due to its massive induction during infections." (PMID 41214213, 2025). "Raised infection markers, i.e., neutrophilic leukocytosis, raised procalcitonin, and elevated C-reactive protein levels, were found in blood parameters." (PMID 40236343, 2025). "In contrast, those who developed postoperative infections tended to exhibit persistently elevated CRP levels beyond postoperative day 4 (often remaining > 100 mg/L)." (PMID 41153812, 2025). "AISI achieved a higher sensitivity (82.93%) and specificity (81.63%) with an area under the curve (AUC) of 0.90, compared to an AUC of 0.74 for CRP, indicating a more effective prognostic capability in assessing severe infections." (PMID 40149510, 2025). "CRP, an acute inflammatory protein synthesized by hepatocytes in response to infection or tissue damage, plays a critical role in the body's innate immune response." (PMID 41169895, 2025). "Although the underlying reason for CRP elevation cannot be determined, mildly elevated CRP is known to occur outside of the normal short‐term responses to infection and trauma in population‐based studies." (PMID 39526963, 2025). "In contrast, CRP, a hepatic acute-phase protein stimulated predominantly by IL-6, demonstrates slower kinetics and remains elevated beyond infection control." (PMID 41281040, 2025). "The eligibility criteria for this systematic review were defined to ensure the inclusion of high-quality, clinically relevant studies assessing the diagnostic accuracy of CRP, PCT, WBC, and NLR in detecting early post-surgical infections." (PMID 40342430, 2025).